ENSG00000278263 (novel protein, identical to IGHV4-4)
Gene: Immunoglobulin variable (V) gene on chromosome 15 (21,742,364 to 21,742,799, reverse strand). Ensembl gene ENSG00000278263.
Gene Ontology:
Molecular function: antigen binding
Biological process: immunoglobulin mediated immune response
Cellular component: extracellular region; plasma membrane
Genetic constraint (gnomAD): Missense variants: 0 observed, 16.47 expected, observed/expected ratio (o/e) 0, 90% interval 0 to 0.18. Synonymous variants: 0 observed, 8.04 expected, observed/expected ratio (o/e) 0, 90% interval 0 to 0.37.
Homologues: Paralogues in human: IGHV4OR15-8 (99% identical), IGHV4-4 (97% identical), IGHV4-59 (92% identical), IGHV4-61 (92% identical), IGHV4-39 (91% identical), IGHV4-28 (90% identical), IGHV4-31 (90% identical), IGHV4-34 (87% identical), IGHV6-1 (62% identical), IGHV2-26 (55% identical), IGHV2-5 (53% identical), IGHV3-11 (53% identical), and 66 more.